NOTCH1 (notch receptor 1)
Diseases named in the same sentence as NOTCH1 in open-access papers (continued):
Sharing a sentence is not in itself a finding about the gene and the disease.
prostate carcinoma (continued). "Inhibiting TAMs phenotype or NOTCH1 signaling could be a viable strategy to impede prostate cancer progression." (PMID 39286635, 2024). "Similarly, in prostate cancer, significantly increased expression of Jagged1 and Notch1 in metastatic tumors, compared to primary lesions, supports the involvement of the Jagged1-Notch1 axis in progression through the induction of the EMT phenotype." (PMID 39766289, 2024). "While Sharp1 was shown to suppress EMT and metastasis by attenuating NOTCH1 signaling in endometrial cancer cells and TGF-β-associated EMT in prostate cancer PC-3 cells, Sharp2 favored TGF-β-associated EMT and interplayed with NOTCH1 to favor cell growth and invasiveness." (PMID 38067152, 2023). "In addition, miR-34a attenuates prostate cancer aggressiveness via down-regulating AR and Notch-1, which are highly expressed in prostate cancer." (PMID 36969009, 2023). "Inhibition of the survival and metastasis of prostate cancer cells by Notch-1 signaling pathway." (PMID 37191432, 2023). "Yang and his colleagues suggested that curcumin could impede prostate cancer cells survival and metastasis via inactivating Notch-1 signaling pathway." (PMID 35585935, 2022). "Notably, silencing GHET1 promotes KLF2 expression, leading to HIF-1α/Notch1 inhibition and subsequent decrease in prostate cancer progression." (PMID 35773731, 2022). "HIF-1α functions as upstream mediator to stimulate Notch1 signaling in prostate cancer." (PMID 35773731, 2022). "The overexpression of ERα and resulting estrogen effects may also activate Notch signaling, e.g., via binding to the NOTCH1 promoter in prostate cancer cells." (PMID 33430387, 2021). "Indeed, Notch1 levels inversely correlated with the expression of E-cadherin in paclitaxel-resistant prostatic cancer, and GSI-mediated inactivation of Notch1 and Notch4 reversed the sensitivity of cancer cells to this taxane." (PMID 34680255, 2021). "Similarly, in prostate carcinoma, the same mechanisms of osteolytic bone metastasis also enhance metastatic potential via the expression of Notch1 and Jag1." (PMID 32092942, 2020). "In addition, NOTCH1 signalling has been shown to increase ABCC1 expression in prostate cancer stem cells." (PMID 32718079, 2020). "Moreover, the expression of Notch1 is positively correlated with the expression of Epithelial-to-Mesenchymal markers, suggesting a role for Notch signaling in prostate cancer aggressiveness." (PMID 32092942, 2020). "Notch1 and its ligands were found to be overexpressed in prostate cancer compared to normal tissue." (PMID 29462871, 2018). "Indeed, in silico analysis of a previously published dataset of human prostate cancer specimens confirms that both NOTCH1 and JAG1 are upregulated at the tumor stage." (PMID 29259971, 2017). "Moreover, the expression of Notch-1 and its ligand Jagged-1 is reported to be related to poor prognosis in breast and prostate cancer." (PMID 28507277, 2017). "Notably, overexpression of Notch1, Notch3, or PlexinD1 downregulated E-cadherin levels in prostate cancer cells." (PMID 27749937, 2016). "Furthermore, we showed in 4 independent prostate cancer patient cohorts that tumors with high Notch1 expression are enriched in GO terms as neurogenesis, response to estrogen stimulus and cell migration." (PMID 27384993, 2016). "Decreased levels of Notch1 protein and mRNA expression were also found in several widely used prostate cancer cell lines (RWPE2, LNCaP, 22rv1, PC3 and DU145) relatively to primary prostate epithelial cells (PrEC or hPEC) or to an immortalized but non-tumorigenic prostate cell line (RWPE1)." (PMID 27384993, 2016). "Moreover, both Notch1 and Notch3 induced PlexinD1 expression in two prostate cancer cell lines PC3 and DU145 and in U87MG (data not shown)." (PMID 27749937, 2016). "Taken together, these results are consistent with a putative dual role of Notch1 gene in prostate cancer, where it may act both as a tumor suppressor and as an oncogene." (PMID 27384993, 2016).
prostate carcinoma (continued). "In the present report we could also show that prostate cancer cells resistant to Notch1 growth inhibitory effects retain Notch-induced upregulation of pro-oncogenic genes also found in Notch_high tumors." (PMID 27384993, 2016). "Notably, both Notch1 and Notch3 expression positively correlates with PlexinD1 levels in prostate cancer, as well as in other tumor types." (PMID 27749937, 2016). "PC3 prostate cancer cells have been shown to express Notch-1 at the protein level." (PMID 26686862, 2016). "Total Notch1 as well as cleaved Notch1 was detected in lung and prostate cancer cells." (PMID 26993595, 2016). "This regulation was not confirmed in a clinical setting or related to chemotherapy in this original paper, although recent support comes from work showing Notch1-dependent up-regulation of MRP1 to increase chemo-resistance in stem-like cells from prostate cancer lines." (PMID 26362310, 2015). "Notch1 expression in bone metastases is significantly higher than that in primary tumorsand, and may play an important role in the bone metastasis of prostate cancer." (PMID 25943311, 2015). "Down-regulation of Notch1 was shown to inhibit prostate cancer cell migration and invasion." (PMID 22970326, 2012). "RNA interference of Notch1 inhibits prostate cancer cell migration and invasion." (PMID 22970326, 2012). "In this study, we demonstrated that CD49f+/ERα + prostate cancer cells associated with basal stem-like and EMT features (EMT-PCBSLCs), as having elevated potential for metastasis, NOTCH1 may be an essential E2-regulated gene pivotal to driving CD49fHi EMT-PCBSLCs subpopulations." (PMID 31122254, 2019). "Furthermore, 10–50 μM curcumin could inhibit the metastasis and survival of DU145 and PC3 prostate cancer cells via the Notch-1 signaling pathway." (PMID 29495626, 2018). "Moreover, inhibition of NOTCH1 reduces prostate cancer cell growth, migration and invasion." (PMID 29259971, 2017). "Interestingly, gene expression profiling of human prostate cancer samples reported in TCGA database indicates significant correlation between Slug expression and both Notch1 and PlexinD1 levels; moreover, similar results were obtained upon analyzing a distinct dataset." (PMID 27749937, 2016). "Similarly in prostate cancer, Notch1 supports cancer cell survival and EMT." (PMID 27281612, 2016). "For example, the transmembrane protein DLK1 has been shown to negatively regulate NOTCH1, which is overexpressed in prostate cancer and is associated with human prostate cancer cell invasion; this suggests that DLK1 downregulation may promote cell invasion via increased NOTCH1 expression." (PMID 23890537, 2013). "In addition, expression of JAG1 protein is increased in metastatic prostate cancer and prostate cancer cells suggesting Notch1 and JAG1 mediated signaling may enhance carcinogenesis." (PMID 20070897, 2010). "Recent research has revealed that the expression level of NOTCH1, BAP1, and TNFSF11 is closely related to bone metastasis in prostate cancer." (PMID 38384328, 2024). "In breast and prostate cancer cells, all PIM kinases can phosphorylate Notch1 at Ser-2152, resulting in localization of the Notch1 intracellular domain in the nucleus and an increase in the transcription of Notch1 target genes." (PMID 38339286, 2024). "Our current study exploited a novel therapeutic intervention targeting AXL, Notch1, Myc, or SIRT1 in an attempt to improve the management of androgen-refractory prostate cancers." (PMID 37960146, 2023). "Although most of the links between Notch receptors and prostate cancer involve NOTCH1, NOTCH2 was also found increased in several prostate cancer cell lines, with the highest levels expressed in the most aggressive ones, whereas NOTCH3/4 were not detectable." (PMID 35954292, 2022). "FEZF1-AS1 is a tumor promoter in prostate cancer via Notch signal activation, overexpressed FEZF1-AS1 contributes to higher levels of Notch1, p21 and Hes1." (PMID 36229883, 2022).
prostate carcinoma (continued). "Notch1 can promote expression levels of MMP-2 and MMP-9 in increasing progression and metastasis of prostate cancer cells." (PMID 35773731, 2022). "Upregulated GHET1 increases prostate cancer proliferation through inducing HIF-1α and Notch 1 signal via negative regulation of Kruppel-like factor 2 (KLF2)." (PMID 36229883, 2022). "Treatment of enzalutamide-resistant prostate cancer cells with the GSI, PF-03084014, or an alternative specific gene knockdown of Notch 1, resensitised cells to enzalutamide treatment, while the drug combination showed efficacy in xenograft models." (PMID 32575680, 2020). "Cell surface molecules such as β1integrins, NOTCH1, DLL1, and IGF-R1 provide important signals for many niches, triggering several downstream signaling pathways essential for prostate cancer progression, stemness and survival." (PMID 31878027, 2019). "Prostate cancer cells with an EMT phenotype induced by PDGFD displayed CSC features, including increased expression of SOX2, NANOG, OCT4, and Notch-1, and enhanced sphere-forming ability and rapid tumor growth in vivo." (PMID 30227608, 2018). "Through Notch1 signaling pathway, MiR200 regulated characteristics of stem cells of EMT phenotype prostate cancer cell." (PMID 25943311, 2015). "The present study used cultured human prostate cancer cells (PC-3, LNCaP, and LNCaP-C4-2B), and dorsolateral prostate tissues from control and SFN-treated TRAMP mice to determine the role of Notch1, Notch2, and Notch4 in anticancer effects of SFN." (PMID 22970326, 2012). "Exposure of human prostate cancer cells (LNCaP, PC-3, and DU145) and a normal human prostate epithelial cell line (PrEC) to PEITC resulted in cleavage (active form) of Notch1 and Notch2, and increased transcriptional activity of Notch." (PMID 22039516, 2011). "We also demonstrate that activation of Notch1 and Notch2 reduces PEITC's ability to inhibit prostate cancer cell migration." (PMID 22039516, 2011). "Similar to prostate cancer cells, PEITC treatment resulted in increased levels of cleaved Notch1 and Notch2 in PrEC cells especially at the 16-hour time point at both 2.5 and 5 μM concentrations." (PMID 22039516, 2011). "The Notch-1 pathway has also regulated PTEN expression in T-ALL and prostate cancer." (PMID 38733531, 2024). "In prostate cancer, MUC1-C has been shown to activate the BAF complex in prostate cancer stem cells, enhancing the expression of NOTCH1 and NANOG, thus promoting self-renewal of tumor stem cells and accelerating the progression of neuroendocrine prostate cancer." (PMID 38361923, 2024). "CCN3 may inhibit the activity of NOTCH1 by binding to the extracellular domain of NOTCH1 in CML, and the CCN3 protein secreted by prostate cancer (PCa) could recruit macrophages and promote their differentiation into the M2 phenotype." (PMID 34393649, 2021). "In terms of prostate cancer, Oktem and colleagues identified CD133high/CD44high DU145 prostate CSCs and found that Jagged1, Delta-like 3, and Notch-1 were respectively upregulated genes in the Notch signaling pathway appearing to be due to malignancy and tumor progression." (PMID 32586404, 2020). "Our experiments establish MDA-9 as a critical regulator of stem cell phenotypes in prostate cancer that are responsible for PCSC maintenance and survival through regulation of multiple stem-regulating molecules such as NOTCH1, C-myc, STAT3, NANOG, OCT4 and SOX2." (PMID 31878027, 2019). "Moreover, knocking down either Notch1 or PlexinD1 similarly decreased the migration of PC3 and DU145 prostate cancer cells in transwell migration assays." (PMID 27749937, 2016). "Consistent with literature data [28,] we also found that knockdown of Notch1 and Notch2 reduces migration of prostate cancer cells irrespective of the androgen-responsiveness." (PMID 22970326, 2012). "PEITC-induced apoptosis in prostate cancer cells is modestly attenuated by knockdown of Notch2, but not by pharmacological inhibition of Notch1 activation." (PMID 22039516, 2011).
prostate carcinoma (continued). "We cultured human PC-3 prostate cancer cells in growth factor defined (epidermal growth factor [EGF] and fibroblast growth factor [FGF]-2) serum-free medium for the enrichment of PCSCs and detected the stem cell markers including Notch-1, Oct-4, and Nanog in PCSCs and parental cells." (PMID 32586404, 2020). "Notably, as previously shown in prostate cancer cells, A-485 selectively suppressed global acetylation of H3K27, without any significant alteration in global H3K27 tri-methylation status in both Notch1 and Notch3 dependent T-cells." (PMID 31001470, 2019). "To demonstrate that Notch1 can act as a tumor suppressor in prostate cancer, we assessed the consequences of i) decreased Notch1 expression on proliferation of non-tumorigenic prostate epithelial cells and ii) increased Notch1 expression in prostate cancer cells with low Notch1 levels." (PMID 27384993, 2016). "Specifically, knockdown of Notch1, Notch2 or Notch4 has no impact at all or only marginal effect on SFN-mediated inhibition of prostate cancer cell migration." (PMID 22970326, 2012).
gastric cancer (95 papers, 2011 to 2025). A primary or metastatic malignant neoplasm involving the stomach. "This is consistent with the research conclusion of Giulia's18, Notch1 activity in gastric cancer is controlled by the epigenetic silencing of the ligand DLL1, and that Notch1 inhibition is associated with the diffuse type of gastric cancer." (PMID 36071128, 2022). "In this study, we observed that Notch 1 mRNA high expression is associated with worsen OS in surgery alone gastric cancer patients and 5-FU based adjuvant gastric cancer patients." (PMID 27363496, 2016). "Changes in the expression of the Notch1 intracellular domain (NICD) differentially expressed in gastric cancer, and the aberrant expression of Notch1 NICD is associated with an advanced tumor stage, tumor metastasis and overall patient survival." (PMID 27363496, 2016). "Aberrant activation of Notch signaling has been described in several tumours and in gastric cancer (GC), activated Notch1 has been associated with de-differentiation of lineage-committed stomach cells into stem progenitors and GC progression." (PMID 22249198, 2011). "Notch-1 mRNA levels are associated with the overall survival of gastric cancer patients." (PMID 33714199, 2021). "Compared to the expression in healthy stomach mucosal tissue, Notch1 expression is significantly higher in gastric carcinoma and is also intimately associated with tumor volume, differentiation grade, depth of invasion and vessel invasion, as confirmed by a tissue microarray." (PMID 28881855, 2017). "Moreover, Notch1 activation has been associated with gastric cancer progression, at least in part through cyclooxygenase-2." (PMID 22249198, 2011). "LncRNA NOTCH1 associated lncRNA in T cell acute lymphoblastic leukemia 1 (NALT1) acts as a regulator to be implicated in the development of gastric cancer (GC)." (PMID 36385135, 2022). "Preclinical studies have shown that blocking Notch1-Hes1 signaling can reverse chemoresistance in gastric cancer." (PMID 40755759, 2025). "This review synthesizes evidence demonstrating how circRNAs modulate Notch activity through miRNA sponging (e.g., circ‐NOTCH 1 promoting gastric cancer metastasis via miR‐637/apelin axis), protein interactions, and peptide encoding." (PMID 40761890, 2025). "Hsa_circ_0089547 can bind to miR-449c-5p, which targets MYC, and the upregulated MYC expression enhances its combination with the NOTCH1 promoter, thereby facilitating the transcription of NOTCH1 in gastric cancer." (PMID 39452835, 2024). "Kai-Wen Hsu reported that the levels of expression of Notch1 and Jagged1 are strongly associated with the levels of phosphorylated STAT3 and Twist in gastric cancer tissues." (PMID 39309860, 2024). "The results showed that the Notch1 upregulation significantly promoted the proliferation, migration, invasion, and vasculogenic mimicry capacity of gastric cancer cells." (PMID 39172098, 2024). "USP24 promotes tumor growth in gastric carcinoma by stabilizing PLK1 to activate NOTCH1 and increase aerobic glycolysis." (PMID 39605891, 2024). "Collectively, these results suggest an important role of IGF2BP2/CSF2/Notch1 axis in regulating MSCs reprogramming in gastric cancer." (PMID 37865637, 2023). "Activation and overexpression of Notch1 promote gastric cancer progression through COX2 expression and the PTEN-ERK1/2 signaling axis, respectively." (PMID 37373228, 2023). "Collectively, these findings indicate that IGF2BP2/CSF2/Notch1 axis reprograms MSCs to promote gastric cancer progression." (PMID 37865637, 2023). "We next aimed to elucidate the involvement of IGF2BP2/CSF2/Notch1 axis in regulating the phenotype and function of MSCs in gastric cancer." (PMID 37865637, 2023). "The identified IGF2BP2/CSF2/Notch1 axis provides additional evidence for the epigenetic regulation of MSCs within the tumor microenvironment and offers a new therapeutic strategy for gastric cancer." (PMID 37865637, 2023).